SOX4 (SRY-box transcription factor 4)
Diseases named in the same sentence as SOX4 in open-access papers (continued):
Sharing a sentence is not in itself a finding about the gene and the disease.
adult T-cell leukemia/lymphoma (1 paper, 2022). A peripheral (mature) T-cell neoplasm linked to the human T-cell leukemia virus type 1 (HTLV-1), adult T-cell leukemia/lymphoma is endemic in several regions of the world, in particular Japan, the Caribbean, and parts of Central Africa. "In adult T-cell leukemia/lymphoma (ATL), HDAC8 expression was driven by an oncogenic cascade of FRA-2/JUND and SOX4 transcription factor, and— together with other two activated genes, GCKR and NAP1—was proven to affect ATL cell growth." (PMID 35887172, 2022).
alcoholism (1 paper, 2021). "Furthermore, disulfiram, an old anti-alcoholism drug, is identified to modulate the miR-30a/SOX4 loop, by upregulating miR-30a expression." (PMID 34234874, 2021).
Autoimmune Disorders (1 paper, 2023). "In addition, SOX4 was suggested to promote the production of high IFN-γ by CCR9+ Th cells, confirming the role of SOX4 in enhancing autoimmune disease progression, since aberrant IFN-γ expression is one of the factors that is associated with autoimmune inflammatory diseases." (PMID 36835620, 2023).
chronic pancreatitis (1 paper, 2012). A chronic inflammatory process causing damage and fibrosis of the pancreatic parenchyma. "By contrast, acinar and ductal epithelial cells from normal pancreas and chronic pancreatitis were not immunoreactive to SOX4 or E2F1." (PMID 23251334, 2012).
cutaneous squamous cell carcinoma (1 paper, 2021). "In addition, LINC00963 regulates the progression of cutaneous squamous cell carcinoma through the miR-1193/SOX4 axis." (PMID 33536018, 2021).
dyslexia (1 paper, 2019). A learning disorder characterized by an impairment in processing written words. "The results highlighted a potential chain link between neuroplasticity-related as well as stress-related genes, such as BDNF, Sox4, mineralocorticoid receptor (MR), and GILZ, leftward asymmetries in the amygdala and selective cerebellum lobules, and tendencies for personality disorders and dyslexia." (PMID 31632253, 2019).
dysplasia (1 paper, 2024). A usually neoplastic transformation of the cell, associated with altered architectural tissue patterns. "Furthermore, copy number variants resulting in entire gene deletion or duplication of SOX4 were associated with skeletal and mesomelic dysplasia as well as cardiac developmental defects but were not causally linked to any neurodevelopmental disorder." (PMID 39518344, 2024).
embryonal carcinoma (1 paper, 2009). A non-seminomatous malignant germ cell tumor characterized by the presence of large germ cells with abundant cytoplasm resembling epithelial cells, geographic necrosis, high mitotic activity, and pseudoglandular and pseudopapillary structures formation. "The Sox4 and Sox11 antisense transcripts were highly expressed in the brain compared to other mouse organs and are differentially expressed in both the proliferating and differentiating neural stem/progenitor cells and P19 (embryonal carcinoma) cells." (PMID 19799774, 2009). "Since both Sox4 and Sox11 are implicated in neuronal differentiation and glial maturation processes, we examined both Sox4 and Sox11 sense and antisense transcript expression in proliferating and differentiating P19 (embryonal carcinoma cells) and in embryonic NSPCs grown as neurospheres." (PMID 19799774, 2009). "The genomic clustering analysis led us to the discovery of spatio-temporal regulation of novel Sox4 and Sox11 antisense transcripts as well as differential regulation of these transcripts in proliferating and differentiating neural stem/progenitor cells (NSPCs) and P19 (embryonal carcinoma) cells." (PMID 19799774, 2009).
eosinophilia (1 paper, 2015). "It has previously been shown that Sox4 transgenic mice exhibit decreased ovalbumin-induced allergic airway disease with lower AHR, IL-5, and eosinophilia." (PMID 26588780, 2015).
gallbladder tumors (1 paper, 2012). "To assess the biological significance of SOX4 expression in gallbladder tumors, we evaluated its expression in 136 PGC samples from PGC patients with full clinical annotation." (PMID 22510499, 2012).
heart failure (1 paper, 2024). Inability of the heart to pump blood at an adequate rate to meet tissue metabolic requirements. "Additionally, a moderate to strong association of the RNA level of SOX4/SOX8 with fibrotic genes was observed, and via a meta-analysis of epigenetics and whole-genome association data, several genomic variants accountable for heart failure were linked to SOX4 or SOX8." (PMID 39518344, 2024).
helminths infection (1 paper, 2021). "Additionally, conditional loss of Sox4 resulted in loss of tuft and enteroendocrine cells and impaired tuft cell hyperplasia after helminths infection." (PMID 33921306, 2021).
Hirschsprung disease (1 paper, 2019). Hirschsprung disease (HSCR) is a congenital intestinal motility disorder that is characterized by signs of intestinal obstruction due to the presence of an aganglionic segment of variable extent in the terminal part of the colon. "The upregulation of miR-369-3p was also found to suppress cell migration and proliferation by targeting SOX4 in Hirschsprung’s disease." (PMID 31337985, 2019).
Hyperglycemia (1 paper, 2025). An increased concentration of glucose in the blood. "Additionally, we observed a predicted increase in Sox4 activity, which has been described as being upregulated in response to hyperlipidemia and hyperglycemia, promoting endothelial to mesenchymal transition, inflammation, and angiogenesis in pathological settings." (PMID 40562785, 2025).
Infertility (1 paper, 2022). "In summary, this study evidences that SOX4 is a new and critical regulator for human endometrial decidualization, and provides insightful information for the pathology of decidualization-related infertility and will pave the way for pregnancy improvement." (PMID 35244538, 2022).
invasive ductal carcinoma (1 paper, 2018). "(A–B) Representative images of SOX4 expression in invasive lobular carcinoma (ILC, classical and pleomorphic) and invasive ductal carcinoma (IDC, low-grade tumor and high-grade tumor) cases in the tissue microarray (TMA) cohort." (PMID 30507376, 2018).
ischemia (1 paper, 2024). A hypoperfusion of the BLOOD through an organ or tissue caused by a PATHOLOGIC CONSTRICTION or obstruction of its BLOOD VESSELS, or an absence of BLOOD CIRCULATION. "Validated targets of miR-129-5p are CAMTA1 (calmodulin-binding transcription factor), indicating a role of calcium under this condition, SOX4 (regulation of Wnt pathway), GALNT1 (modifying glycan structures), EIF2C3 and HMGB1, which has been shown to protect against ischemia/reperfusion injury." (PMID 39201485, 2024).
kidney injury (1 paper, 2024). Trauma to the kidney. "This research sought to assess the possible impact of the SOX4/EZH2 axis on ferroptosis in the pathogenesis of CaOx-induced kidney injury and evaluate the protective effect of EZH2 inhibition." (PMID 38169402, 2024).
kidney stones (1 paper, 2024). "SOX4 was one of the transcription factors screened out and was upregulated in kidney stones due to the RNA sequencing and western blot results." (PMID 38169402, 2024).
liver cirrhosis (1 paper, 2024). "By analyzing the Co-DEGs associated with the progression and prognosis of liver cirrhosis, we identified five key genes: SOX4, LGALS3, SERPINE2, CD52, and LPXN." (PMID 39194690, 2024).
metastatic prostate carcinoma (1 paper, 2013). A carcinoma that arises from the prostate gland and has spread to other anatomic sites. "Among these, SOX4, STAT3 and STAT5B are known regulators of metastatic prostate cancer through the regulation of genes involved in miRNA processing, transcriptional regulation, and developmental pathways." (PMID 23782521, 2013).
mood disorder (1 paper, 2023). A cognitive disorder a disturbance in which the person's mood is hypothesized to be the main underlying feature. "The most significant CpG (cg22274825; p = 5.10 × 10–6) was located at the South Shore of an island linked to the gene SOX4, a gene also linked to mood disorders and immune-related processes in prior research." (PMID 37664245, 2023).
myocardial ischemia (1 paper, 2024). A disorder of cardiac function caused by insufficient blood flow to the muscle tissue of the heart. "In addition, suppression of circHDAC9, a circular RNA, could dramatically lower the level of SOX4 and significantly attenuate myocardial ischemia/reperfusion injury by mediating the miR-671-5p/SOX4 signaling pathway." (PMID 39518344, 2024).
myotonic dystrophy (1 paper, 2023). An inherited progressive disorder affecting the muscles. "CNBP is dysregulated in iPSC derived from patients with myotonic dystrophy, whereas SOX4 and DPPA4 are transcription factors shown to be dynamically regulated during endoderm induction from iPSCs." (PMID 36631981, 2023).
Nephropathy (1 paper, 2024). A nonspecific term referring to disease or damage of the kidneys. "Furthermore, SOX4 has been recognized as a novel biomarker of T2DM-induced nephropathy." (PMID 39498440, 2024).
pituitary tumour (1 paper, 2020). "Links between these factors and the pituitary are known for PTMA and SOX4, as PTMA nuclear staining has been linked to pituitary tumour size, and SOX4 is involved in pituitary development, as shown in both zebrafish and human tissues." (PMID 32183012, 2020).
postmenopausal osteoporosis (1 paper, 2023). Metabolic disorder associated with fractures of the femoral neck, vertebrae, and distal forearm. "In addition, reduced expression of SOX4 was found in patients with postmenopausal osteoporosis while decreased Sox4 expression in mice resulted in reduced bone mineral density." (PMID 36614288, 2023).
preeclampsia (1 paper, 2026). Preeclampsia is a hypertensive disorder of pregnancy that is characterized by new-onset hypertension with proteinuria presenting after 20 weeks of gestation, and depending on mild or severe forms may initially present with severe headache, visual disturbances, and hyperreflexia. "Overall, our integrated approach reveals the regulatory mechanism by which activin A, SOX4, and miR-103a-3p regulate human trophoblast invasion and EVT differentiation, highlighting their potential as early diagnostic biomarkers for preeclampsia." (PMID 41963302, 2026).
psoriasis (1 paper, 2020). An autoimmune condition characterized by red, well-delineated plaques with silvery scales that are usually on the extensor surfaces and scalp. "However, there were also long-range interactions (CHiCAGO score ≥ 5) between psoriasis-associated fragments and SOX4 over 950 kb in all cell types." (PMID 32366252, 2020).
rectal tumor (1 paper, 2012). "Of these genes KIFC1 and SOX4 were also significantly overexpressed in rectal tumor tissues than paracancerous tissues." (PMID 23158542, 2012).
rhabdomyosarcoma (1 paper, 2020). A rare aggressive malignant mesenchymal neoplasm arising from skeletal muscle. "This approach enabled us to identify several novel and promising rhabdomyosarcoma CSC-specific targets, e.g., ALDH6A1, SOX4, PAX3, CDH15, downregulated MIR145, or phosphorylated RYK, which warrant validation in subsequent mechanistic studies." (PMID 31941033, 2020). "Importantly, SOX4 is highly expressed in embryonal rhabdomyosarcoma compared with normal muscle and knockdown of SOX4 leads to a significant decrease in MYOD1 levels and impaired rhabdomyosarcoma cell survival." (PMID 31941033, 2020).
soft tissue sarcoma (1 paper, 2020). A malignant neoplasm arising from muscle tissue, adipose tissue, blood vessels, fibrous tissue, or other supportive tissues excluding the bones. "This is in agreement with our survival analysis on soft-tissue sarcomas demonstrating that upregulated expression of ALDH6A1 but not ALDH1A1 or ALDH3A1 significantly correlates with poor survival when combined with other genes identified in our model, i.e., CDH15, MYOD1, SOX4, ARMCX1, and RYK." (PMID 31941033, 2020).
stomach adenocarcinoma (1 paper, 2021). "Among the main TFs-HRi identified, we highlight four TFs (SETD3, HOX3B, FOXA1, and SOX4) for being widely reported in association with stomach adenocarcinoma." (PMID 34416858, 2021).
Stroke (1 paper, 2025). Sudden impairment of blood flow to a part of the brain due to occlusion or rupture of an artery to the brain. "Specifically, PPARα KO led to increased expression levels of Gadd45b, Nppa, Hdc, Lcn2, Il6, Sox4, Marcksl1, Saa3, Ucn2, Met, Dusp10, Elovl7, Ngf, C3, Il11, Hmox1, Alox5, Tnfsf9, Angptl4, Plin2, H19, Csf2rb, Atf3, and Col7a1 following stroke." (PMID 40362325, 2025).
uveal melanoma (1 paper, 2012). A melanoma derived from melanocytes of the uveal tract. "Though the possible role of mda-9/syntenin in nuclear functions has yet to be determined in uveal melanoma, recent findings indicated that mda-9/syntenin colocalizes with the SOX-4 transcription factor in the nucleus and stabilizes its expression in different tumor cells." (PMID 22267972, 2012).
ventricular septal defect (1 paper, 2025). The presence of a defect (opening) in the septum that separates the two ventricles of the heart. "Mettl3 deficiency-induced downregulation of MEF2A, SOX4, and SOX11 expression could lead to congenital cardiac defects, including left pulmonary stenosis, ventricular septal defects, and right ventricular hypoplasia." (PMID 40303284, 2025).
tumor (312 papers, 2007 to 2026). "Bioinformatics analysis further suggests that the SOX4/PTBP2 axis is associated with the tumor immune microenvironment and the sensitivity to several anti-cancer drugs." (PMID 42255218, 2026). "The association between SOX4 and tumor immune infiltration as well as drug sensitivity was explored by combining bioinformatics analysis." (PMID 42255218, 2026). "A recent study identified miR-92b-3p as a key regulator of tumor-associated angiogenesis by directly targeting SRY-box transcription factor 4 (SOX4)." (PMID 40284522, 2025). "SOX4 was associated with myeloid cell development, apoptosis, and tumorigenesis, indicating that tumor-associated DCs were functionally heterogeneous." (PMID 37533434, 2023). "The expression levels, prognostic values, genetic mutation, and DNA promoter methylation of SOX4 across tumor types were explored via systematic bioinformatics analysis." (PMID 37958409, 2023). "SOX4 expression level was strongly associated with unfavorable prognoses, genetic mutations, and DNA methylation levels across different tumor types." (PMID 37958409, 2023). "In conclusion, SOX4 was widely overexpressed in tumor tissues and associated with unfavorable prognoses, genetic mutation, and DNA methylation level, especially in LIHC." (PMID 37958409, 2023). "We also explored the genetic mutation and DNA promoter methylation level of SOX4 in different tumor types." (PMID 37958409, 2023). "While we did not observe a difference in VEGFA levels between the DSG2‐high and DSG2‐low patients in the non‐MS cohort, other genes associated with tumour vascularization (e.g. SOX4 and SOX2) were co‐expressed with DSG2." (PMID 34245117, 2022). "As a crucial metastasis-associated regulator, SOX4 induces the chemotaxis of human umbilical vein endothelial cells, angiogenesis, and tumor growth in HCC by activating CXCL12, therefore facilitating HCC metastasis." (PMID 35267473, 2022). "Mechanically, miR-30d exerted its tumor suppressive effect by directly targeting SOX4, which caused inhibition of the PI3K-AKT signaling pathway." (PMID 33824274, 2021). "Differential SOX4 expression and its correlation with tumor stage as well as its diagnostic and prognostic value were analyzed on the oncomine and GEPIA websites." (PMID 33995626, 2021). "Studying the molecular changes associated with the tumor-suppressive action of Metformin we found that the oncogene SOX4, which is upregulated in solid tumors and associated with poor prognosis, was induced by Wnt/β-catenin signaling and blocked by Metformin." (PMID 29977599, 2018). "The authors report reduced tumor progression and number in Sox4-deficient mice compared to wild type, indicating an oncogenic activity of Sox4 in the skin." (PMID 28587635, 2017). "We for the first time made comprehensive analysis of miR-204 and SOX4 with clinicopathological parameters in patients and determined that miR-204 and SOX4 were dramatically associated with lymph node metastasis and tumor stages." (PMID 28133610, 2017). "We, therefore, propose that one underlying mechanism by which miR-31 suppresses tumor cell invasion is by directly targeting SOX4 and indirectly targeting EZH2 and HDAC3." (PMID 25644061, 2015). "In some cancers, the expression of SOX4 mRNA was particularly elevated in metastases and this was associated with the recurrence and prognosis of these tumor types." (PMID 26578818, 2015). "Loss of SOX4 led to a significant increase in miR-31 expression and strongly inhibited tumor cells proliferation, migration and invasion." (PMID 25644061, 2015). "CTNNB1/SOX4 expression in CRC tumors was significantly associated with tumor-infiltrating CAFs." (PMID 38203779, 2024). "Recently, the association between SOX4 dysregulation and tumour progression has been reported." (PMID 37251541, 2023).